RETN (resistin)
Diseases named in the same sentence as RETN in open-access papers (continued):
Sharing a sentence is not in itself a finding about the gene and the disease.
Cachexia (2 papers, 2014 to 2020). Severe weight loss, wasting of muscle, loss of appetite, and general debility related to a chronic disease. "Despite the fact that resistin is associated with cachexia development, it cannot be used as a diagnostic marker of this process." (PMID 25049439, 2014). "Since there was higher prevalence of metastatic cancers in cachectic patients (P = 0.013), we reanalyzed the data using two-way ANOVA and found both cachexia (P = 0.012) and metastatic status (P < 0.001) to be independently associated with serum resistin." (PMID 25049439, 2014). "We found that cachexia and metastatic status were independently associated with serum resistin." (PMID 25049439, 2014). "Authors suggest that resistin may contribute to the cachexia related weight loss through its participation in catabolic processes." (PMID 25049439, 2014). "The overall accuracy of resistin as a potential indicator of cachexia was moderate (AUC = 0.71 (95% CI: 0.60–0.81), P < 0.001)." (PMID 25049439, 2014). "Our study is the first one, which analyzed effects of interaction between cachexia, distant metastasis, and resistin levels in GEC." (PMID 25049439, 2014). "Analysis of covariance demonstrated that cachexia status (P = 0.036) and not BMI (P = 0.286) was significantly associated with serum resistin." (PMID 25049439, 2014).
carbohydrate metabolism disorders (2 papers, 2024). "In diagnosing carbohydrate metabolism disorders, the use of adiponectin, TNF-α, IL-6, resistin, IL-1β and IL-23 in women, and IL-23 in men should be considered." (PMID 39769504, 2024).
cardiac ischemia (2 papers, 2022). "Considering this, we were rather surprised to find resistin downregulated in the early phase after cardiac ischemia." (PMID 36388122, 2022). "In rodent models of cardiac ischemia, resistin either aggravated cardiac dysfunction or was protective." (PMID 36388122, 2022). "Resistin is overexpressed during myocardial ischemia through the ERK/MAPK pathway." (PMID 35204357, 2022).
cardiomyopathy (2 papers, 2018 to 2024). A disease of the heart muscle or myocardium proper. "Hyperglycemic rats had increased serum levels of adipokines (omentin, resistin, and TNF-α) and cardiomyopathy markers (cardiac troponin I and Creatine kinase-MB)." (PMID 38227584, 2024). "In hyperglycemic rats, the level of fasting blood glucose, and serum level of resistin, omentin, TNF-α, and cardiomyopathy biomarkers significantly increased (P < 0.05)." (PMID 38227584, 2024).
carotid atherosclerosis (2 papers, 2018 to 2020). A thickening and loss of elasticity of the walls of carotid arteries that occur with formation of atherosclerotic plaques. "Specifically, with the worsening of carotid atherosclerosis, circulating levels of resistin and visfatin gradually increased, while the level of vaspin decreased." (PMID 29848323, 2018).
childhood asthma (2 papers, 2013 to 2025). "SQSTM1, HSPA5, and A2M which directly interact with RETN could serve as the potential therapeutic targets in childhood asthma." (PMID 41550933, 2025). "The resistin protein-protein interaction network analysis further suggests that SQSTM1, HSPA5 and A2M might serve as the potential therapeutic targets in childhood asthma." (PMID 41550933, 2025).
chronic hepatitis C (2 papers, 2017). "In patients with chronic hepatitis C virus infection, low serum levels of resistin are associated with the presence of fibrosis and may therefore be a biochemical marker of fibrosis." (PMID 28061755, 2017).
chronic obstructive pulmonary disease (2 papers, 2020 to 2021). A chronic and progressive lung disorder characterized by the loss of elasticity of the bronchial tree and the air sacs, destruction of the air sacs wall, thickening of the bronchial wall, and mucous accumulation in the bronchial tree. "Serum resistin was elevated in the patients with chronic obstructive pulmonary disease after Chlamydia pneumoniae infection." (PMID 34858392, 2021).
co-infection (2 papers, 2021 to 2025). "Finally, resistin could identify high-risk patients before they developed significant complications as a result of this viral co-infection." (PMID 40724556, 2025). "Furthermore, the research found that patients with higher resistin levels demonstrated a trend of having an increased number of viral co-infections." (PMID 40724556, 2025).
cognitive decline (2 papers, 2022 to 2025). "Simple assays of leptin/adiponectin ratios, resistin levels, or composite adipokine panels might identify individuals at metabolic risk for cognitive decline." (PMID 41155642, 2025). "Adiponectin/resistin ratios correlate with insulin sensitivity, systemic inflammation, and cognitive decline." (PMID 41155642, 2025).
Cognitive impairment (2 papers, 2017 to 2025). Abnormal cognition is characterized by deficits in thinking, reasoning, or remembering. "Human studies have linked higher resistin levels with cognitive impairment, increased brain atrophy, and greater Aβ burden, although its specific mechanistic role in AD remains an area of active investigation." (PMID 41155642, 2025). "In both rodent models and human postmortem brain tissue, resistin co-localizes with Aβ plaques and tau tangles; higher resistin levels in plasma and CSF correlate with hippocampal atrophy, cognitive impairment, and faster functional decline." (PMID 41155642, 2025).
coronary aneurysm (2 papers, 2016 to 2020). Abnormal balloon- or sac-like dilatation in the wall of coronary vessels. "Our previous study has shown high levels of serum Resistin in KD patients with coronary aneurysms." (PMID 27800490, 2016). "In KD children, circulating resistin levels are higher in those with coronary artery aneurysm compared with controls and KD without coronary artery aneurysm, and positively correlated with CRP." (PMID 33081064, 2020).
diabetic cardiomyopathy (2 papers, 2018 to 2021). Diabetic cardiomyopathy is a disorder of the heart muscle in people with diabetes. "Equally interesting is the evidence about the potential involvement of resistin in diabetic cardiomyopathy." (PMID 34129696, 2021). "We have previously reported that diabetic hearts express high levels of resistin while overexpression of resistin in adult rat hearts gives rise to a phenotype resembling diabetic cardiomyopathy." (PMID 30353146, 2018).
Dyslipidaemia (2 papers, 2014 to 2023). "Dyslipidaemia is characterised by a high FFA level; an imbalance of leptin, resistin, and adiponectin; and a deficiency of ghrelin in the acute and early recovery periods of MI." (PMID 24433403, 2014).
eczema (2 papers, 2020 to 2023). "The levels of adiponectin and resistin were inversely associated to the severity of eczema as measured by the SCORAD scale, according to a study evaluating the potential utility of adipokines as AD severity biomarkers." (PMID 36614274, 2023). "Serum resistin was associated with lipocalin-2 changes when considering the whole AD group (r = 0.37; p = 0.009); the association was notably strengthened in patients with severe eczema (r = 0.60; p = 0.003)." (PMID 32899610, 2020). "Further, the levels of adiponectin and resistin were inversely related to the intensity of eczema assessed using the SCORAD index." (PMID 32899610, 2020). "There were insignificant differences in serum resistin between mild eczema (median: 11.8 ng/mL; min–max: 9.7–18.4 ng/mL) and severe eczema patients (median: 10.8 ng/mL; min–max: 7.4–16.8 ng/mL) (p = 0.090)." (PMID 32899610, 2020). "Serum resistin was significantly lower in AD patients compared to healthy controls (p < 0.001) and it progressively decreased with eczema severity as determined by SCORAD (r = −0.38; p = 0.008)." (PMID 32899610, 2020). "Aside from the most hitherto time-tested and studied connection between the increase in blood leptin and AD symptoms, the present findings conversely show decreases in adiponectin and resistin as the presage of eczema severity." (PMID 32899610, 2020). "Further, the levels of adiponectin and resistin were inversely related to the intensity of eczema." (PMID 32899610, 2020). "Thus, apart from the previously studied role of leptin in AD, this study directs attention to adiponectin and resistin as the candidate adipokines possibly involved in shaping eczema severity, which may help predict disease exacerbations and develop targeted therapeutic interventions." (PMID 32899610, 2020). "In this study, we addressed the contribution of adipokines to AD eczema based on the assessment of blood levels of adiponectin, resistin, leptin, lipocalin-2, and vaspin in adult non-obese patients suffering from chronic extrinsic childhood-onset AD." (PMID 32899610, 2020).
end-stage renal disease (2 papers, 2017 to 2021). "The serum concentration of resistin is elevated in patients with end-stage renal disease, and there is a strong correlation between resistin and hsCRP concentrations and resistin and residual renal function in CKD patients." (PMID 28494192, 2017).
Genetic obesity (2 papers, 2013 to 2017). "In rodents, resistin is highly expressed in adipose tissue, and circulating levels of resistin are increased during diet-induced or genetic obesity." (PMID 28061755, 2017). "Steppan CM reported that increased circulating resistin levels in diet-induced and genetic obesity could be decreased by rosiglitazon." (PMID 23776497, 2013).
Graves disease (2 papers, 2016 to 2022). Graves' disease is an autoimmune disorder that leads to overactivity of the thyroid gland (hyperthyroidism).It is caused by an abnormal immune system response that causes the thyroid gland to produce too much thyroid hormones. "To date, few but controversial studies have reported about resistin concentrations in hyperthyroid patients, especially in Graves' disease (GD)." (PMID 27637079, 2016).
hemorrhagic fever (2 papers, 2018 to 2021). An infectious disease caused by certain viruses or bacteria that can damage the walls of tiny blood vessels, making them leak, and can hamper the blood's ability to clot and cause severe, life-threatening illness. "In patients with Crimean-Congo hemorrhagic fever, caused by tick-borne virus, plasma resistin was elevated and higher concentrations associated with severe disease, defined by the manifestations of bleeding." (PMID 30517161, 2018).
hemorrhagic stroke (2 papers, 2009 to 2013). A stroke caused by a bleed on the brain. "Several studies suggest that resistin levels are proportional with the magnitude of injury and indicative for prognosis following ischemic or hemorrhagic stroke." (PMID 24070260, 2013).
Hypoglycemia (2 papers, 2011 to 2019). A decreased concentration of glucose in the blood. "This hormone may play a role in maintenance of metabolic neonatal homeostasis; high circulating resistin levels at term gestation could be advantageous to the infant by promoting hepatic glucose production and preventing hypoglycemia after birth." (PMID 21760816, 2011). "Higher serum resistin levels have been found in term infants compared to preterm infants, and it has been suggested that newborns could benefit from these higher concentrations of circulating resistin, facilitating the production of hepatic glucose and preventing hypoglycemia after delivery." (PMID 31185620, 2019).
idiopathic pulmonary fibrosis (2 papers, 2010 to 2022). Idiopathic pulmonary fibrosis (IPF) is a nonneoplastic pulmonary disease that is characterized by the formation of scar tissue within the lungs in the absence of any known cause. "Pulmonary fibrosis due to accumulation of asbestos and silica is correlated with high serum resistin levels." (PMID 35592858, 2022). "The murine equivalent of resistin is FIZZ-1 (found in inflammatory zone 1) and has been previously associated with fibrotic regions of lung fibrosis models." (PMID 20300636, 2010).
infertile (2 papers, 2015 to 2019). "The results of this study indicate that resistin levels are increased in infertile patients with leukocytospermia and with varicocele and are correlated with impaired sperm quality, LPO, and semen redox imbalance." (PMID 31772701, 2019). "The data from this research showed that infertile patients affected by leukocytospermia and varicocele had increased levels of resistin with respect to fertile men." (PMID 31772701, 2019). "In a previous paper, we demonstrated that semen resistin was increased in patients with leukocytospermia and smoking habit and also in infertile patients when we compare them with control subjects with unknown reproductive potential." (PMID 31772701, 2019). "Thus, we determined resistin levels in seminal plasma of infertile patients affected by leukocytospermia or varicocele and in a group of fertile individuals." (PMID 31772701, 2019).
leukopenia (2 papers, 2016 to 2025). "Plasma concentrations of resistin have been reported to be elevated in horses with an inflammatory condition such as fever, tachycardia and leukocytosis–leukopenia." (PMID 41441039, 2025).
malaria (2 papers, 2019 to 2023). Malaria is a serious and sometimes fatal disease caused by a parasite that commonly infects a certain type of mosquito which feeds on humans. "Within innate myeloid cells, malaria drove changes to monocytes consistent with the induction of immunosuppressive MS1-like monocytes, which have high expression of alarmins S100A8/A9, along with RETN and ALOX5AP and reduced expression of MHC class II." (PMID 37968278, 2023).
metastatic cancer (2 papers, 2014 to 2024). A carcinoma which has spread from the original site of growth to another anatomic site. "In this review, we examined the impact of adipocytes on cancer by describing the adipocyte-secreted factors that are involved in controlling metastatic cancer, focusing on adipokines, such as adiponectin, leptin, visfatin, chemerin, resistin, apelin, and omentin." (PMID 38238841, 2024).
migraine (2 papers, 2022 to 2025). "In the present trial, 44 patients with episodic migraine were enrolled and underwent 2- months nanocurcumin or placebo supplementation to evaluate the effects of nano-curcumin on resistin, visfatin, and MCP-1 levels and clinical manifestation of headache in migraine patients." (PMID 35606882, 2022). "The resistin, visfatin, and MCP-1 concentration increase in migraine patients' serum or cerebrospinal fluid." (PMID 35606882, 2022). "These adipokines such as resistin, visfatin, and MCP-1 have abundant receptors in the central nervous system, are involved in migraine pathogenesis." (PMID 35606882, 2022).
morbid obesity (2 papers, 2012 to 2024). An excess of body weight, normally defined as an individual with a body mass index greater than 35 or a body weight greater than one hundred percent of ideal body weight. "The present study investigated fasting ghrelin and resistin levels in patients undergoing either restrictive (SG) or malabsorptive (OAGB) procedures for morbid obesity before and after (1 week, 1 month, 3 months, and 1 year) surgery." (PMID 38833355, 2024).
myositis (2 papers, 2012 to 2016). "Accordingly, the role of resistin in the pathology of muscle tissue in myositis is underpinned by its association with parameters of disease activity in the group of patients with myositis associated autoantibody Jo-1." (PMID 22577940, 2012). "The assessment of resistin staining intensity in inflammatory infiltrates of the sections from muscle biopsies revealed a mean intensity of 1.8 in myositis and 1.6 in DM patients on the 0 to 3 scale." (PMID 22577940, 2012). "Importantly, we found that serum resistin levels were strongly associated with CRP and global disease activity, and a trend was also observed towards correlation between resistin levels and myoglobin in patients with myositis-specific anti-Jo-1 antibody in contrast to anti-Jo-1 negative patients." (PMID 22577940, 2012).
neuroblastoma (2 papers, 2021 to 2024). Neuroblastoma (NB) is the most common solid, extracranial childhood tumor. "Here, we investigated the impact of palmitic acid on insulin responsiveness and its potential effects on TLR4 expression and resistin action in human SH-SY5Y neuroblastoma cell line." (PMID 33686181, 2021).
non-small cell lung carcinoma (2 papers, 2020 to 2024). A group of at least three distinct histological types of lung cancer, including non-small cell squamous cell carcinoma, adenocarcinoma, and large cell carcinoma. "The analysis of resistin level in cachectic patients with non-small cell lung cancer (NSCLC) show an increasing tendency of resistin in comparison to non-cachectic ones." (PMID 32660156, 2020). "An observational study revealed that while leptin and adiponectin were not directly implicated in disease alterations in non-small cell lung carcinoma, resistin, functioning as a pro-inflammatory cytokine, might play a role in the pathogenesis of weight loss in NSCLC patients." (PMID 38263093, 2024).
pancreatic cancer (2 papers, 2018 to 2024). "Regarding cancer risk, circulating resistin levels have been correlated with several types of cancer, including colorectal, breast, lung, endometrial, gastroesophageal, prostate, renal, and pancreatic cancer." (PMID 39184804, 2024). "Circulating resistin concentrations have been associated with several types of cancer, including colorectal, breast, lung, uterine, gastrointestinal, prostate, kidney, and pancreatic cancer." (PMID 39184804, 2024). "In agreement with the findings of other research teams in other cancers, resistin levels were higher in high grade pancreatic cancers, as compared to the levels in the lower grade cancers." (PMID 30131543, 2018). "Pancreatic cancer patients with negative resistin staining had double the relapse-free survival (18 months), in contrast to the patients whose tumors stained positive for resistin (9 months)." (PMID 30131543, 2018).
pregnancy disorder (2 papers, 2021 to 2025). A disorder that is related to pregnancy. "Recent studies demonstrated that some adipokines such as resistin, visfatin and tumor necrosis factor α (TNF-α) are dysregulated in GDM and contribute to metabolic complications typical of this pregnancy disorder." (PMID 34652617, 2021). "A growing number of studies suggest that various adipokines including adiponectin, leptin, visfatin, resistin and tumor necrosis factor α (TNF-α) are dysregulated in GDM and might have pathological significance and a prognostic value in this pregnancy disorder." (PMID 34652617, 2021).
Prostate tumor (2 papers, 2023). "This strongly suggests that resistin-exposed PC3 cells secrete EVs with cargo molecules that induce invasion and metastasis, highlighting the importance of resistin in prostatic tumor progression." (PMID 38137922, 2023). "In a study in which Korean patients participated, it was observed that as the Gleason score increased, there was an increase in the expression of resistin in prostate tumor tissue." (PMID 38137922, 2023). "Epidemiological and translational studies report that an increase in plasma levels and tissue expression of resistin increases the aggressiveness of prostate tumor cells." (PMID 38137922, 2023). "However, the role of resistin in the migration, invasion, and secretion of EVs in invasive prostate tumor cells remains to be studied." (PMID 38137922, 2023). "Prostate tumor weight and growth were reduced by walnuts, accompanied by a decline in plasma IGF-1, resistin and LDL." (PMID 37237848, 2023).
pulmonary TB (2 papers, 2015 to 2024). "Clinical research has demonstrated that pulmonary tuberculosis is characterized by diminished circulating adiponectin and leptin levels, as well as augmented resistin levels." (PMID 38263093, 2024).